UBE2M (ubiquitin conjugating enzyme E2 M)
Diseases named in the same sentence as UBE2M in open-access papers (continued):
Sharing a sentence is not in itself a finding about the gene and the disease.
tumor (continued). "Multivariate analysis showed that upregulated UBE2M expression could be a significant factor for predicting poor survival (P < 0.01) when UBE2M expression level, TNM stage, AFP, tumor size, and tumor differentiation were included based on univariate analysis." (PMID 32012120, 2020). "Higher NAE1 expression was correlated with larger tumor size, poorer Edmondson’s grade, presence of microvascular invasion, poorer TNM, and poorer BCLC stage, and higher UBE2M expression was correlated with multiple tumors and the presence of microvascular invasion." (PMID 29846044, 2018).
cancer (24 papers, 2014 to 2026). A tumor composed of atypical neoplastic, often pleomorphic cells that invade other tissues. "This revealed 11 samples across six different cancer types with a nonsynonymous mutation in a neddylation-associated gene: four with a UBE2M mutation, five with a NAE1 mutation, one with a NEDD8 mutation, and one with a mutation in the NEDD8-binding domain of CUL3." (PMID 36068196, 2022). "Increasing lines of evidence have strongly suggested that UBE2M acts as an oncogene, which is altered in over two-thirds of all human cancers." (PMID 39138151, 2024). "While UBE2M, is only recently starting to be envisaged as a cancer player, FN1 and RECQL4 are two well-known oncogenes." (PMID 39657701, 2024). "The inhibitor of UBE2M involved in the neddylation of Cullin1-4, arctigenin, effectively inhibited the malignant phenotype of cancer cells." (PMID 39062453, 2024). "Overexpression of both UBE2M and UBE2F in cancer cells is associated with increased cell proliferation and poor survival." (PMID 36690633, 2023). "Elevated expression of NEDD8, SMURF1, NAE1, and UBE2M have been found to correlate with cancer development and poor prognosis." (PMID 37717015, 2023). "Currently, there are several inhibitors that target the UBE2M-defective in cullin neddylation protein 1 (DCN1) interaction to treat cancer." (PMID 33827629, 2021). "Recent and ongoing investigations have proven that UBE2M and UBE2F are overexpressed in cancer cells and associated with cell proliferation and poor survival rates." (PMID 33827629, 2021). "Although UBE2M overexpression has been identified, few studies have been conducted on its clinical significance in cancers." (PMID 32012120, 2020). "Recent studies described the isolation and development of small compounds that inhibit DCNL1 function by blocking interaction with acetylated UBE2M and its potency in killing certain types of cancer." (PMID 30587576, 2019). "Elevated expression of CUL1 and CUL4A is observed in cancers, and UBE2M expression is elevated upon irradiation in cancer cells, suggesting the UBE2M-Cullin components are required for survival of the cancer cells." (PMID 25025768, 2014). "Therefore, depletion of UBE2M is an effective strategy for enhancing the sensitivity of cancer cells to DNA damage." (PMID 39138151, 2024). "Accordingly, the inhibition of JUNB neddylation and protection from degradation by blocking the UBE2M-ITCH interaction could be beneficial for certain cancer treatments." (PMID 37717015, 2023). "Moreover, UBE2M depletion increases cancer cell sensitivity towards niraparib, fluorouracil, and oxaliplatin (chemotherapeutic agents)." (PMID 37717015, 2023). "We utilized multilevel TCGA data to investigate whether somatic mutations in UBE2M, NAE1, NEDD8, or the NEDD8-binding domain of CUL3 can be found in cancers with NRF2 activation." (PMID 36068196, 2022). "In summary, there is enough evidence to prove that UBE2M may be a promising therapeutic target for cancer treatment." (PMID 33827629, 2021). "Our data supports the idea that UBE2M could potentially be an alternative therapeutic target for increasing genome instability in cancer cells." (PMID 25025768, 2014). "However, similar to OTUB1, UBE2M is widely reported to play an oncogenic role in cancers." (PMID 35864871, 2022). "Notably, MLN4924, which is also known as pevonedistat, is a first-in-class inhibitor of the NAE used in cancer treatment and regulates UBE2M and UBE2F in different ways; MLN4924 causes a dose- and time-dependent increase in UBE2M levels but a decrease in UBE2F levels." (PMID 33827629, 2021). "Compared to normal tissues, the mRNA levels of UBE2M are elevated in 17 different kinds of human cancers, while the mRNA levels of UBE2F are elevated in 12 different types of human cancers." (PMID 36690633, 2023).
cancer (continued). "There is substantial evidence indicating that both UBE2M and UBE2F are crucial in controlling cancer cell growth, immune function, and survival." (PMID 37717015, 2023). "Recently, several reviews have provided detailed overviews of the roles of both UBE2M and UBE2F in various cancers." (PMID 37717015, 2023). "On the other hand, UBE2M and OTUB1 were negatively enriched in some cancer-related or immune response-related pathways, such as PI3K/AKT signaling in cancer, the JAK/STAT signaling pathway, pathways in cancer, and the chemokine signaling pathway." (PMID 35864871, 2022). "UBE2M and OTUB1 are both cancer-related genes and have been reported to regulate the immune response and antitumor immunity." (PMID 35864871, 2022). "This review provides insights into the mechanism of UBE2M and UBE2F and emphasizes these two E2 enzymes as appealing therapeutic targets for the treatment of cancers." (PMID 33827629, 2021). "UBE2M, FN1, and RECQL4, for example, fell among our top 12 common-cancer seed hubs." (PMID 39657701, 2024). "This suggests that targeting the interaction between UBE2M and IAP could be a promising strategy for developing anti-cancer drugs." (PMID 37717015, 2023). "By interacting with miR-23a-3p/23b-3p/23c, SNHG17 upregulates the expression of UBE2M and OTUB1, which have been demonstrated to play critical roles in the tumorigenesis of human cancers, more importantly promoting cancer cell immunosuppression and resistance to cytotoxic stimulation." (PMID 35864871, 2022). "UBA3, UBE2M and RBX1 are important for the proliferation and apoptosis of cancer cells." (PMID 35880551, 2022). "Taken together, UBE2M may be a novel and appealing target, and UBE2F may become a potential target for cancer treatment." (PMID 33827629, 2021). "Moreover, the UBE2M and c-Cbl axis have been shown to promote the neddylation of the EGFR, leading to its sorting and degradation, which prevents the overactivation of EGFR in cancer cells." (PMID 37717015, 2023). "However, as a pseudogene of UBE2M, barely transcribed in the liver, there is no adequate information and report of its functions in cancer research." (PMID 36214767, 2022). "UBE2M and UBE2F may become promising targets for cancer treatment." (PMID 33827629, 2021).
infection (4 papers, 2013 to 2025). The state of being infected such as from the introduction of a foreign agent such as serum, vaccine, antigenic substance or organism. "However, more evidence is needed to confirm the different roles of UBE2M in macrophages in the pathogenesis of various infections caused by different pathogens, and the exact mechanisms involved also need to be further investigated." (PMID 39675717, 2025). "Knockout of UBE2M in Jurkat cells exhibited the most potent inhibition of infection of all the validated genes except for the positive control, CD4." (PMID 36744886, 2023). "We find that knockout of UBE2M which was one of the top hits in each of the screens had the strongest phenotype in the spreading infections for both viruses tested." (PMID 36744886, 2023). "We found similar results if we measured the RT activity in the supernatant at day 5 or at day 7 as the primary readout instead of AUC, and find that at both time points, knockout of UBE2M which was one of the top hits in each of the screens had the strongest phenotype in the spreading infections." (PMID 36744886, 2023).
gastrointestinal tumor (1 paper, 2023).
UBE2M also shares sentences with these, for which no sentence is quoted: liver cancer (5 papers); glioblastoma (4); colorectal cancer (3); cholangiocarcinoma (2); intrahepatic cholangiocarcinoma (2); pancreatic cancer (2); renal cell carcinoma (2); acute kidney injury (1); bacterial infections (1); colon cancer (1); colorectal adenocarcinoma (1); depression (1); head and neck tumor (1); hematopoietic cancers (1); infectious disease (1); inflammatory bowel disease (1); influenza A (H1N1) virus infection (1); kidney diseases (1); liver fibrosis (1); lung adenocarcinoma (1); lung squamous cell carcinoma (1); lymph node metastasis (1); macrosomia (1); melanoma (1); nasopharyngeal carcinoma (1); necrotizing enterocolitis (1); osteoarthritis (1); Parkinson disease (1); peripheral neuropathy (1); promyelocytic leukemia (1).
A further 4 diseases each share a sentence with UBE2M in 1 paper.